TYROBP (transmembrane immune signaling adaptor TYROBP)
Description:
Adapter protein which non-covalently associates with activating receptors found on the surface of a variety of immune cells to mediate signaling and cell activation following ligand binding by the receptors. TYROBP is tyrosine-phosphorylated in the ITAM domain following ligand binding by the associated receptors which leads to activation of additional tyrosine kinases and subsequent cell activation. Also has an inhibitory role in some cells. Non-covalently associates with activating receptors of the CD300 family to mediate cell activation. Also mediates cell activation through association with activating receptors of the CD200R family (By similarity). Required for neutrophil activation mediated by integrin (By similarity). Required for the activation of myeloid cells mediated by the CLEC5A/MDL1 receptor. Associates with natural killer (NK) cell receptors such as KIR2DS2 and the KLRD1/KLRC2 heterodimer to mediate NK cell activation. Also enhances trafficking and cell surface expression of NK cell receptors KIR2DS1, KIR2DS2 and KIR2DS4 and ensures their stability at the cell surface. Associates with SIRPB1 to mediate activation of myeloid cells such as monocytes and dendritic cells. Associates with TREM1 to mediate activation of neutrophils and monocytes. Associates with TREM2 on monocyte-derived dendritic cells to mediate up-regulation of chemokine receptor CCR7 and dendritic cell maturation and survival. Association with TREM2 mediates cytokine-induced formation of multinucleated giant cells which are formed by the fusion of macrophages. Stabilizes the TREM2 C-terminal fragment (TREM2-CTF) produced by TREM2 ectodomain shedding which suppresses the release of pro-inflammatory cytokines. In microglia, required with TREM2 for phagocytosis of apoptotic neurons (By similarity). Required with ITGAM/CD11B in microglia to control production of microglial superoxide ions which promote the neuronal apoptosis that occurs during brain development (By similarity). Promotes pro-inflammatory responses in microglia following nerve injury which accelerates degeneration of injured neurons (By similarity). Positively regulates the expression of the IRAK3/IRAK-M kinase and IL10 production by liver dendritic cells and inhibits their T cell allostimulatory ability (By similarity). Negatively regulates B cell proliferation. Required for CSF1-mediated osteoclast cytoskeletal organization (By similarity). Positively regulates multinucleation during osteoclast development (By similarity).
Synonyms: DAP12; KARAP; PLO-SL; PLOSL; PLOSL1
Tractability: Small molecule: a structure with a bound ligand is known. Antibody: UniProt places it where antibodies can reach, with high confidence; its Gene Ontology location is reachable by antibodies, with high confidence; UniProt predicts a signal peptide or a membrane-spanning region; the Human Protein Atlas places it where antibodies can reach. PROTAC: its protein half-life has been measured.
Gene: Protein-coding gene on chromosome 19 (35,904,401 to 35,908,301, reverse strand). Ensembl gene ENSG00000011600.
Subcellular location: Cell membrane
Subcellular location (Human Protein Atlas): Plasma membrane
Pathways (Reactome):
Immune System: DAP12 interactions; DAP12 signaling; Immunoregulatory interactions between a Lymphoid and a non-Lymphoid cell; Neutrophil degranulation
Cell-Cell communication: Signal regulatory protein family interactions
Developmental Biology: Other semaphorin interactions
Gene Ontology:
Molecular function: identical protein binding; molecular adaptor activity; protein binding; protein homodimerization activity; protein-macromolecule adaptor activity; signaling receptor binding
Biological process: amyloid-beta clearance; cellular response to amyloid-beta; myeloid leukocyte activation; natural killer cell mediated immunity; negative regulation of B cell proliferation; negative regulation of type I interferon production; osteoclast differentiation; positive regulation of macrophage fusion; positive regulation of protein localization to cell surface; protein stabilization; stimulatory C-type lectin receptor signaling pathway; stimulatory killer cell immunoglobulin-like receptor signaling pathway; actin cytoskeleton organization; apoptotic cell clearance; cellular defense response; forebrain development; intracellular signal transduction; microglial cell activation involved in immune response; negative regulation of interleukin-10 production; negative regulation of long-term synaptic potentiation; negative regulation of transforming growth factor beta1 production; neutrophil activation involved in immune response; positive regulation of gene expression; positive regulation of interleukin-1 beta production; positive regulation of interleukin-6 production; and 18 more
Cellular component: cell surface; plasma membrane; membrane; secretory granule membrane
Genetic constraint (gnomAD): Loss-of-function variants: 14 observed, 17.18 expected, observed/expected ratio (o/e) 0.81, 90% interval 0.54 to 1.27. The upper end of that interval is the gene's LOEUF score, 1.27, which puts it in group 5 of 6, group 1 being the genes least tolerant of losing a copy. Missense variants: 161 observed, 157.23 expected, observed/expected ratio (o/e) 1.02, 90% interval 0.9 to 1.17. Synonymous variants: 73 observed, 71.25 expected, observed/expected ratio (o/e) 1.02, 90% interval 0.85 to 1.25.
Homologues: Orthologues: chimpanzee TYROBP (97% identical), rabbit TYROBP (78% identical), guinea pig TYROBP (75% identical), macaque TYROBP (74% identical), mouse Tyrobp (73% identical), pig TYROBP (73% identical), rat Tyrobp (71% identical), dog TYROBP (53% identical), zebrafish tyrobp (36% identical).
Diseases named in the same sentence as TYROBP in open-access papers:
TYROBP is named in the same sentence as 154 diseases in open-access papers, as found by Europe PMC text mining. Sharing a sentence is not in itself a finding about the gene and the disease. The quoted sentences say what the papers report.
Nasu-Hakola disease (54 papers, 2008 to 2025). "In line with the mild osteopetrosis and thalamic hypomyelinosis observed in the DAP12−/− mice, loss-of-function mutations in TYROBP (encoding DAP12) are associated with Nasu-Hakola disease, which is characterized by presenile dementia and bone cysts." (PMID 41301467, 2025). "Mutations in TYROBP have been associated with various diseases, including Nasu-Hakola disease, which is a rare neurodegenerative disorder that affects the brain and bones." (PMID 37207157, 2023). "Although TREM2 and TYROBP mutations are causative for Nasu-Hakola disease and increase the risk of AD, the link between these two dementias is still unclear." (PMID 36002854, 2022). "Loss-of-function mutations in the gene that encodes TYRO protein kinase-binding protein (TYROBP) cause Nasu-Hakola disease, a heritable disease resembling Alzheimer’s disease (AD)." (PMID 35386591, 2022). "Whereas heterozygous variants in TREM2 are associated with AD, homozygous variants in TREM2 or its binding partner DAP12/TYROBP cause polycystic lipomembranous osteodysplasia with sclerosing leukoencephalopathy (PLOSL), also known as Nasu-Hakola disease (NHD)." (PMID 33422057, 2021). "Mutations in TYROBP cause Nasu-Hakola disease, in which the neurodegenerative pathology is defined as a primary microglial disorder." (PMID 32450896, 2020). "Biallelic (both alleles carry a variant, homozygous or compound heterozygous) loss-of-function variants in either TYROBP or TREM2 cause Nasu-Hakola disease (NHD) known also as polycystic lipomembranous osteodysplasia with sclerosing leukoencephalopathy (PLOSL)." (PMID 40301889, 2025). "Finally, deletion and premature termination, loss-of-function mutations in the TYROBP gene are associated with Nasu-Hakola disease, a rare recessively-inherited disease associated with early-onset dementia." (PMID 36002854, 2022). "Additionally, TREM2 or TYROBP loss of function mutations result in Nasu-Hakola disease (NHD), also known as polycystic lipomembranous osteodysplasia with sclerosing leukoencephalopathy (PLOSL), characterized by microglial activation and dementia." (PMID 29040522, 2018). "Nasu-Hakola disease (NHD) is a rare autosomal recessive disorder caused by mutations in the TYROBP or TREM2 genes." (PMID 41510405, 2025). "Biallelic loss-of-function mutations in TREM2 or TYROBP (encoding its cytoplasmic adaptor molecule, also known as DAP12) cause Nasu-Hakola disease, also known as polycystic lipomembranous osteodysplasia with sclerosing leukoencephalopathy (PLOSL)." (PMID 40448228, 2025). "Nasu-Hakola disease (NHD) is a rare autosomal recessive disorder characterized by progressive presenile dementia and bone cysts, caused by variants in either TYROBP or TREM2." (PMID 31396216, 2019). "Biallelic loss-of-function variants in TYROBP and TREM2 cause autosomal recessive presenile dementia with bone cysts known as Nasu-Hakola disease (NHD, alternatively polycystic lipomembranous osteodysplasia with sclerosing leukoencephalopathy, PLOSL)." (PMID 40301889, 2025). "Loss-of-function mutations in the TYROBP gene cause Nasu-Hakola disease (NHD), also known as polycystic lipomembranous osteodysplasia with sclerosing leukoencephalopathy (MIM 221770)." (PMID 35386591, 2022). "Patients with Nasu-Hakola disease, a neurodegenerative disease caused by mutations in TYRO protein tyrosine kinase-binding protein (TYROBP, also known as DAP12) or TREM2, present with cerebrovascular changes and bilateral basal ganglia calcifications localized to the walls of blood vessels." (PMID 35309892, 2022). "The Nasu-Hakola disease, a disorder affecting both brain and bone, is known to be related to the malfunctioning of TREM2 or TYROBP." (PMID 23662159, 2013).
Alzheimer disease (47 papers, 2013 to 2025). A progressive, neurodegenerative disease characterized by loss of function and death of nerve cells in several areas of the brain leading to loss of cognitive function such as memory and language. "TYROBP expression is increased in Alzheimer’s disease (AD) patients, and its deficiency in AD mice showed to be neuroprotective and immune-inflammatory therapeutic, which eventually slowed/arrested the progression of pathological late-onset sporadic AD." (PMID 36685283, 2022). "TYROBP is the downstream adaptor and putative signaling partner for several receptors implicated in Alzheimer’s disease (AD), including SIRP1β, CD33, CR3, and TREM2." (PMID 36002854, 2022). "This macrophage population is marked by upregulation of the TYROBP network, a damage-response pathway first implicated in the control of amyloid plaques by microglia in Alzheimer’s disease." (PMID 34554929, 2021). "It is likely that TYROBP plays a role in neuroinflammation in that loss of DAP12 function delays disease progression in a mouse Alzheimer disease model." (PMID 32731618, 2020). "Some other TREM2 variants contribute to the risk of Alzheimer’s disease (AD) and frontotemporal dementia, while deleterious TYROBP variants are globally extremely rare and their role in neurodegenerative diseases remains unclear." (PMID 40301889, 2025). "Notably, the aberrant TYROBP expression is related to the genesis and progression of various disorders, and it is related to the pathogenic mechanism of Alzheimer's disease and cognitive dysfunction." (PMID 38549127, 2024). "Additionally, TYROBP has been implicated in the pathogenesis of Alzheimer’s disease and other neurodegenerative diseases." (PMID 37207157, 2023). "TYROBP mutations have also been detected in patients with Alzheimer’s disease (AD)." (PMID 35386591, 2022). "Besides, the upregulated genes of both Neil1- and Neil2-deficient EBs + RA were significantly enriched for the pathway term ‘TYROBP causal network’, associated with late-onset Alzheimer’s disease." (PMID 31566562, 2019). "Together with its receptor, triggering receptor expressed on myeloid cells 2 (TREM2), TYROBP contributes to the onset and progression of Alzheimer's disease by impacting various cellular processes such as phagocytosis, cytokine production, and inflammation." (PMID 38017559, 2023). "The abnormal expression of TYROBP has been reported to take part in numerous diseases, such as Alzheimer’s disease, breast cancer, osteosarcoma and renal cell carcinoma." (PMID 36978098, 2023). "TYRO protein tyrosine kinase-binding protein (TYROBP) plays an important role in the pathogenesis of Alzheimer’s disease (AD)." (PMID 36602538, 2023). "TYROBP was reported as a potential prognostic biomarker of clear cell renal cell carcinoma and was highly related with Alzheimer’s disease." (PMID 35865544, 2022). "Previous studies have reported TREM2 as a key player in Alzheimer’s disease and TYROBP as key gene for AS." (PMID 36552740, 2022). "Increasing evidence has demonstrated that TYROBP strengthen the phagocytotic ability of microglia and inhibited the immune responses in Alzheimer’s disease." (PMID 36466903, 2022). "Recent studies revealed a critical role of TREM2/TYROBP signaling in the regulation of microglial phagocytosis in Alzheimer's disease and other neurological diseases." (PMID 33225612, 2020). "However, TYROBP genetic variants may predispose to early onset Alzheimer disease." (PMID 32731618, 2020). "Similarly, reduced TYROBP function in mouse models confers resistance to demyelination as well as tau hyperphosphorylation and dystrophic neurites in Alzheimer's disease." (PMID 40506843, 2025). "Yin and colleagues suggested that TYROBP may be involved in the development of Alzheimer's disease by affecting microglial cell activity and the formation of related inflammatory plaques." (PMID 35607269, 2022). "Disruption of the TYROBP signalling network has also been demonstrated in Alzheimer’s disease." (PMID 32450896, 2020).
Alzheimer disease (continued). "TYROBP/DAP12 forms complexes with ectodomains of immune receptors (TREM2, SIRPβ1, CR3) associated with Alzheimer’s disease (AD) and is a network hub and driver in the complement subnetwork identified by multi-scale gene network studies of postmortem human AD brain." (PMID 30283031, 2019). "The TREM2 and TYROBP mRNAs reported recently in Late-onset Alzheimer's disease also yield a correlation of R2 of 0.999 (N = 6) using similar informatics analysis, but HCRT informatics inclusion would suppress the correlation slightly as compared to the EPO informatics inclusion." (PMID 23662159, 2013). "In contrast, deletion of TREM2 or the adaptor tyrosine kinase-binding protein (TyroBP or DAP12), which binds to TREM2, leads to an excess of the pro-inflammatory phenotype, which decreases microglial survival and causes amyloid plaque deposition in experimental models of Alzheimer's disease (AD)." (PMID 35844208, 2022). "However, CBDN may be able to infer such important regulators from gene expression data alone, as it identifies the important regulator TYROBP in Alzheimer’s disease." (PMID 27556418, 2016). "In one of these studies, TYROBP was identified as a key regulator for an immune- and microglia-specific transcriptional network, that was differentially expressed between control and late-onset Alzheimer's disease postmortem brains, highlighting its potential role in disease status." (PMID 26002684, 2015). "TREM2 forms a receptor signaling complex with TYROBP, which triggers the activation of immune responses in macrophages and dendritic cells, and the functional polymorphism of TREM2 is reported to be associated with neurodegenerative disorders such as Alzheimer’s disease (AD)." (PMID 26332043, 2015). "Gene network analysis by Zhang and colleagues identified a microglia specific module that includes TYROBP, the signaling adaptor protein of TREM2, as a key node of networks in late onset Alzheimer’s disease." (PMID 28923083, 2017). "On the other hand, DAMs, as a distinct microglia phenotype, showed an upregulation of the ITAM-signaling molecule TYROBP while concurrently downregulating microglial checkpoint genes including CX3CR1, as identified by single-cell RNA-seq in Alzheimer’s disease mouse models." (PMID 38529039, 2024). "Although the “TYROBP casual network” was not reported previously for SS, recent publications reveal that TYROBP is overactivated during other autoimmune diseases, such as Huntington’s, Alzheimer’s disease and osteoarthritis." (PMID 36341342, 2022).
dementia (23 papers, 2008 to 2025). Loss of intellectual abilities interfering with an individual's social and occupational functions. "Enrichment of rare coding variants in TYROBP was detected in a cohort of early-onset AD patients, while no predicted pathogenic TYROBP variants were detected in a cohort of Turkish dementia patients." (PMID 40301889, 2025). "The effect remained significant when APOE ε4 (rs429358) allele was included in the same model, suggesting that TYROBP increases the risk of AD and dementia independently of APOE ε4." (PMID 40301889, 2025). "In this study we show that monoallelic 5.2-kb TYROBP deletion is a novel risk factor for AD, leading to twofold increased risk of AD and dementia with an earlier onset age in the monoallelic carriers when compared to non-carriers." (PMID 40301889, 2025). "Human patients with loss-of-function mutations in the DAP12-encoding TYROBP gene mainly displayed presenile dementia and bone cysts." (PMID 37190045, 2023). "A common clinical manifestation in NHD patients and some of the genetic variants of TREM2 or TYROBP is early-onset dementia." (PMID 33115519, 2020). "To determine whether the association of TYROBP locus with dementia and AD was driven by the TYROBP deletion proxy markers or other variants in the locus, we produced regional association plots of the TYROBP locus." (PMID 40301889, 2025). "Importantly, our findings revealed that the Finnish TYROBP deletion associates with an increased risk and earlier onset of dementia and AD in the monoallelic carriers." (PMID 40301889, 2025). "Loss of TYROBP has resulted in presenile dementia with bone cysts." (PMID 36685283, 2022). "Further studies in large populations will be essential to evaluate whether associations exist between TYROBP and other dementias." (PMID 36002854, 2022). "For both dementia and AD, the TYROBP deletion proxy marker rs1244787406-G significantly lowered the age at first diagnosis." (PMID 40301889, 2025). "Homozygous mutations in TYROBP (encoding the TREM2 ligand DAP12) or TREM2 cause Nasu–Hakola disease associated with progressive, early-onset dementia, bone cysts, and demyelinating lesions in the CNS." (PMID 40400621, 2025). "This approach allowed us to detect increased risk and earlier age of onset for AD and dementia among the monoallelic TYROBP deletion carriers compared to noncarriers, which was not dependent on APOE status." (PMID 40301889, 2025). "We show that monoallelic TYROBP deletion associates with an increased risk and earlier onset age of AD and dementia when compared to noncarriers." (PMID 40301889, 2025). "Individuals that are homozygous for loss of function mutations in either TREM2 or TYROBP (DAP12) suffer from polycystic lipomembranous osteodysplasia and sclerosing leukoencephalopathy (PLOSL) which is characterized by early onset dementia and cystic bone lesions." (PMID 24893973, 2014). "DAP12/TYROBP and LY96 were among the genes whose expression was significantly affected in successful aging and in dementia in oldest-old persons, albeit in different directions." (PMID 19865478, 2009).